MALAT1 (metastasis associated lung adenocarcinoma transcript 1)
Diseases named in the same sentence as MALAT1 in open-access papers (continued):
Sharing a sentence is not in itself a finding about the gene and the disease.
renal fibrosis (continued). "In patients with obstructive nephropathy, lncRNA MATAL1 levels were positively related to hydronephrosis, together with ECM deposition and the expression of α-SMA, indicating that enriched expression of MALAT1 might lead to the renal fibrosis pathogenesis in patients with obstructive nephropathy." (PMID 32752143, 2020). "Moreover, DHA can attenuate ON-induced renal fibrosis through the MALAT1/miR-145/FAK axis." (PMID 32203053, 2020). "Furthermore, we explored whether DHA, an effective antimalarial drug, attenuates renal fibrosis through MALAT1." (PMID 32203053, 2020). "Another study reported that METTL3 modifies m6A methylation on long-non-coding RNA (lncRNA) MALAT1 to upregulate MALAT1 expression, which thereby promotes transforming growth factor β1 (TGF-β1)-induced renal fibrosis through miR-145/FAK signaling." (PMID 37815911, 2024). "It positively regulates MALAT1 in TGF-β1-treated HK2 cells and affects the MALAT1/miR-145/FAK pathway in renal fibrosis, leading to renal fibrosis." (PMID 37841018, 2023). "In TGF-β1-treated tubular epithelial cells, m6A modification exerts a regulatory role in positively regulating MALAT1 expression by engaging METTL3, suggesting the involvement of m6A modification in the MALAT1/miR-145/focal adhesion kinase (FAK) pathway of renal fibrosis." (PMID 37841018, 2023). "Thus, m6A modifications can afflict MALAT1 expression and possibly exert effects on the MALAT1/miR-145/FAK pathway in renal fibrosis during CKD." (PMID 35534472, 2022). "In addition, m6A is elevated in renal fibrosis induced by TGF-β1, and it participates in the MALAT1/miR-145/focal adhesion kinase signaling pathway, which affects the pathological process of chronic renal diseases." (PMID 36237191, 2022). "Even if this is not the first study for MALAT1 in renal fibrosis, our study indeed further revealed the role of MALAT1 in ON-induced renal fibrosis and the mechanism by which METTL3 positively regulates MALAT1." (PMID 32203053, 2020). "In conclusion, the present study reveals that the expression profile of MALAT1/miR-145/FAK may be a potential biomarker for the diagnosis and treatment of ON-induced renal fibrosis in CKD." (PMID 32203053, 2020). "Thus, we revealed that m6A modifications can modulate MALAT1 in TGF-β1-treated HK2 cells and possibly affect the MALAT1/miR-145/FAK pathway in renal fibrosis." (PMID 32203053, 2020). "Similarly, lncRNA MALAT1 serves as an endogenous miR-143 sponge to enhance protein Zinc Finger E-Box Binding Homeobox 2, a DNA-binding transcription factor involved in the expression of mesenchymal genes and E-cadherin, which further promotes EMT in renal fibrosis." (PMID 32752143, 2020).
Hepatic steatosis (16 papers, 2016 to 2026). Steatosis is a term used to denote lipid accumulation within hepatocytes. "The primary aim of this investigation was to assess the contribution of MALAT1 in mitigating OA-induced hepatic steatosis in HepG2 cells upon treatment with Ex-4." (PMID 40002783, 2025). "As a member of the lncRNA family, MALAT1 is a multi-functional lncRNA and an important regulator in hepatic fibrosis, liver regeneration, cancer, and fatty liver diseases." (PMID 35145971, 2021). "The role of MALAT1 was demonstrated in several metabolic disorders, including hepatic steatosis and IR, by the stabilization of nuclear SREBP-1c through inhibiting its ubiquitination." (PMID 32368256, 2020). "MALAT1 has been shown to modulate key regulatory pathways involved in lipid homeostasis, including the regulation of lipogenesis and lipid oxidation, making it a potential player in the pathogenesis of hepatic steatosis and related metabolic disorders." (PMID 40002783, 2025). "Moreover, MALAT1 was demonstrated to possess the ability to promote hepatic steatosis and IR." (PMID 34828775, 2021). "MALAT1 significantly inhibits palmitic acid-induced lipid accumulation and increases expression of SREBP-1c, an important regulator of cholesterol and fatty acid synthesis in abnormal lipid metabolism and fatty liver disease." (PMID 35145971, 2021). "However, to date, no previous studies have investigated the role of MALAT1 in reducing hepatic steatosis in response to GLP-1RAs." (PMID 40002783, 2025). "However, the function of MALAT1 in the improvement of hepatic steatosis has not been studied." (PMID 26935028, 2016). "However, the effect of MALAT1 on hepatic steatosis has not been investigated." (PMID 26935028, 2016).
oral squamous cell carcinoma (16 papers, 2015 to 2025). "For instance, MALAT1 (metastasis-associated lung adenocarcinoma transcript 1) was found to be overexpressed in oral squamous cell carcinoma, and high expression of this lncRNA was related to poor prognosis." (PMID 27338266, 2016). "Among numerous lncRNAs, OIP5-AS1, MALAT1, UCA1, CCAT1, and MEG3 have been implicated in oral squamous cell carcinoma, and these lncRNAs were included in this study." (PMID 40568293, 2025). "MALAT1 has been shown to be associated with various human diseases, including neoplastic and non-neoplastic diseases, such as oral squamous cell carcinoma, psoriasis, recurrent miscarriage, major adverse cardiac and cervical events." (PMID 36829256, 2023). "LncRNA HOTAIR and MALAT-1 were confirmed to be detectable in the saliva of oral squamous cell carcinoma (OSCC) patients, suggesting that lncRNAs may be potential markers for diagnosing cancer." (PMID 28112249, 2017). "Oral squamous cell carcinoma (OSCC) is the most common malignant tumor of the oral cavity, and long non-coding (lnc)RNA of metastasis-associated lung adenocarcinoma transcript 1 (MALAT1) was recently reported to play a crucial role in OSCC development and progression." (PMID 34268119, 2021). "In oral squamous cell carcinoma (OSCC), MALAT1 developed the DDP resistance of OSCC by upregulating P-glycoprotein expression." (PMID 36829256, 2023).
Cerebral ischemia (15 papers, 2020 to 2025). Restriction of arterial blood supply to the brain associated with insufficient oxygenation to support the metabolic requirements of the tissue. "This study aimed to investigate the potential role and molecular mechanism of lncRNA metastasis associated lung adenocarcinoma transcript 1 (MALAT1) in cerebral ischemia/reperfusion injury." (PMID 33750458, 2021). "Metastasis-associated lung adenocarcinoma transcript 1 (MALAT1) long non-coding RNA (lncRNA) also activates autophagy and protects against cerebral ischemia by binding to miR-200c-3p and upregulating Sirt1 expression." (PMID 33132849, 2020). "Also, Wang and his colleagues confirmed that the long non-coding RNA (lncRNA) Metastasis-associated lung adenocarcinoma transcript 1 (MALAT1) additionally triggers autophagy and offers protection against cerebral ischemia." (PMID 39846000, 2024). "Experimental studies after reversible cerebral ischemia revealed that lncRNA MALAT1 is upregulated in cerebral microvessels." (PMID 41245147, 2025). "In contrast, some studies supported the neuroprotective role of Malat1 in cerebral ischemia–reperfusion injury." (PMID 35991562, 2022). "Resent study had demonstrated that MALAT1 also play an important role in cerebral ischemia/reperfusion injury." (PMID 32138732, 2020). "Knockdown of Malat1 in mice alleviated inflammatory injury after cerebral ischemia, and overexpression of Malat1 aggravated ischemic brain inflammation." (PMID 33134293, 2020). "The present study identified MALAT1 as a regulator of cerebral ischemia/reperfusion injury by regulating miR-145 to target AQP4." (PMID 32138732, 2020). "A recent study found that knockdown of lncRNA MALAT1 attenuated the inflammatory injury after brain ischemia, whereas overexpression of MALAT1 exacerbated ischemic brain inflammation." (PMID 33192490, 2020). "However, high expression of lncRNA MALAT1 resulted in a reduction of the effects of cerebral ischemia and a decrease in the level of pro-inflammatory factors." (PMID 41245147, 2025). "Another study revealed reduced expression of lncRNA MALAT1 in the blood of patients after cerebral ischemia, which was closely associated with the negative effects of ischemia." (PMID 41245147, 2025). "MALAT1 was overexpressed in diabetic cerebral ischemia models in vivo and in vitro." (PMID 37013491, 2023). "However, the specific roles and mechanisms by which Malat1 regulates pyroptosis and necroptosis in cerebral ischemia–reperfusion injury have remained unclear." (PMID 35991562, 2022). "LncRNA MALAT1 regulates cerebral ischemia-reperfusion injury through miR-145." (PMID 34820386, 2021). "In conclusion, the results of the present study demonstrated that inhibition of MALAT1 could protect against cerebral ischemia/reperfusion injury by downregulating AQP4 levels via miR-145." (PMID 32138732, 2020). "However, an miR-145 inhibitor reversed the protection effects of MALAT1, indicating that MALAT1 silencing protects against cerebral ischemia-reperfusion injury through miR-145." (PMID 32138732, 2020). "Therefore, MALAT1 affects AQP4 expression by competitively binding to miR-145, thereby promoting cerebral ischemia-reperfusion injury, suggesting that MALAT1 may become a new therapeutic target for the treatment of cerebral ischemic stroke." (PMID 36275741, 2022). "MALAT1 affects AQP4 expression by competitively binding to miR-145, thereby promoting cerebral ischemia-reperfusion injury." (PMID 36275741, 2022). "Also, PD administration in rats elevated MALAT1 expressions, reduced cerebral infarct volume and brain inflammation, protected cerebrovascular endothelial cells and BBB integrity after cerebral ischemia." (PMID 35346266, 2022). "Moreover, it was reported that Malat1 was highly expressed in OGD/R-induced astrocyte injury models, and that its silencing protected against cerebral ischemia–reperfusion injury by downregulating AQP4 levels via miR-145." (PMID 35991562, 2022).
Cerebral ischemia (continued). "Taken together, our study confirmed that MALAT1 promotes cerebral ischemia-reperfusion injury by affecting AQP4 expression through competitively binding miR-145, indicating that MALAT1 might be a new therapeutic target for treatment cerebral ischemic stroke." (PMID 32138732, 2020).
leukemia (15 papers, 2013 to 2025). A malignant (clonal) hematologic disorder, involving hematopoietic stem cells and characterized by the presence of primitive or atypical myeloid or lymphoid cells in the bone marrow and the blood. "Strikingly, high plasma levels of LINC01268 (p = 0.0018), GAS5 (p = 0.0008) or MALAT1 (p = 0.0348) are also associated with a poor overall-survival while high levels of LINC01268 correlate with a shorter leukemia-free-survival." (PMID 34638230, 2021). "Metastasis-associated lung adenocarcinoma transcript 1 (MALAT1) is one of the most studied lncRNAs in cancer that has been established to play an oncogenic role and be overly expressed in numerous human cancers, including leukemia." (PMID 38777995, 2024). "While the physical interaction of lncRNA MALAT1 with the SIPA1 leukemia oncogene has been experimentally validated and recapitulated in our network, MALAT1 is linked to other crucial oncogenes in the two linked modules, and co-expressed with NEAT1, another well-known lncRNA in the context of cancer." (PMID 31142264, 2019). "The MALAT1 gene is involved in the regulation of the differentiation and expansion of leukemia cells." (PMID 40699783, 2025). "Collectively, we established that a functional RNP complex, which is composed of MALAT1, leukemia-related fusion proteins, and m6A methyltransferases, regulates the mRNA transcript export process in nuclear speckles." (PMID 32703936, 2020). "We further established an ascites NOD-SCID mouse model using human leukemia cell line NB4 harboring PML-RARα to reveal the function of MALAT1 and m6A in vivo." (PMID 32703936, 2020). "Given the important role of MALAT1 in leukemia, it would be interesting to test these small molecules in the future and determine whether they are effective in reducing drug resistance in leukemia." (PMID 37148556, 2023). "To verify the biological significance of the lincRNA–promoter network, we found that two genes closely related to the differentiation of leukemia cells, NEAT1 and MALAT1, interact closely at the chromatin level." (PMID 40699783, 2025). "The frequent contact between MALAT1 and NEAT1 in 3D space is potentially related to the functional interaction between these two proteins in leukemia cells." (PMID 40699783, 2025). "The most known examples are MALAT1 and NEAT1 expressed in different neoplasms, including B-cell lymphomas and leukemias." (PMID 36275462, 2022).
mantle cell lymphoma (15 papers, 2016 to 2024). Mantle cell lymphoma is a rare form of malignant non-Hodgkin lymphoma affecting B lymphocytes in the lymph nodes in a region called the ``mantle zone''. "In mantle cell lymphoma, MALAT1 was found upregulated and associated with advanced disease stage and lower overall survival, similarly to our obtained results." (PMID 35008626, 2021). "Furthermore, it was recently found that the association of MALAT1 with EZH2 promoted mantle cell lymphoma development, in which MALAT1 overexpression was linked with reduced overall survival." (PMID 29685978, 2018). "MALAT1 is abundantly expressed and associated with reduced overall survival of mantle cell lymphoma (MCL) patients." (PMID 29739426, 2018). "For example, the siRNA-induced knockdown of MALAT1 in mantle cell lymphoma (MCL) cell lines has resulted in decreased cell viability and colony formation, increased cell apoptosis, and cell cycle arrest at the S/G1 transition." (PMID 34944942, 2021). "In mantle cell lymphoma, elevated MALAT1 expression correlates with poor prognosis and reduces overall survival, and knockdown of MALAT1 results in an enhanced level of P21 and P27 through the modulation of EZH2." (PMID 31752930, 2019). "lncRNA MALAT1 has already been reported to bind with EZH2 in mantle cell lymphoma." (PMID 31830649, 2020). "MALAT1 is also overexpressed in mantle cell lymphoma (MCL) patients and MCL cell lines, and its high expression has been associated with high and intermediate prognostic risk and poor OS." (PMID 38255996, 2024). "Wang’s study suggested that MALAT1 over-expression increases the proliferation of mantle cell lymphoma (MCL) cells by activating EZH2 and inhibiting p21 and p27 genes in vitro." (PMID 28561778, 2017). "Notably, MALAT1 is found upregulated in several type of cancers, also including MCL mantle cell lymphoma, acting through different mechanisms (as discussed in paragraph 3.3)." (PMID 35456025, 2022). "MALAT1 is upregulated in tumour tissues from mantle cell lymphoma (MCL) patients compared to normal B-cells, and knockdown of MALAT1 results in cell cycle arrest due to upregulation of p21 and p27 through enhancer of zeste homolog 2 (EZH2), a component of the polycomb repressive complex 2 (PRC2)." (PMID 30134619, 2018). "The basal expression level of MALAT1 was determined in six mantle cell lymphoma derived cell lines (Z-138, Mino, REC-1, Jeko-1, JVM2 and Granta-519), the MCL cells with higher expression of MALAT1 (Mino and Jeko-1) which were used for additional experiments." (PMID 27998273, 2016).
Obesity (15 papers, 2014 to 2026). Accumulation of substantial excess body fat. "The results of this part illustrated that abnormal metabolism, obesity and abnormal androgen were associated with MALAT1 expression in GCs." (PMID 38424234, 2024). "Considering that PCOS was often associated with obesity, we also focused on the MALAT1 expression difference between controls and PCOS cases with normal weight and obesity (Obe)." (PMID 38424234, 2024). "Accordingly, we performed this case-control study with 150 children and adolescents as a pilot investigation into the association between MALAT1 rs3200401 and H19 rs217727, and obesity in children and adolescents aged between 5 and 17 years old." (PMID 37104004, 2023). "Our results confirmed the association between SNP rs3200401 in MALAT1 and the risk of obesity (p = 0.0009)." (PMID 37104004, 2023). "We aimed to evaluate the possible associations between the SNPs rs3200401 in MALAT1 and rs217727 in H19, and an individual’s risk of obesity." (PMID 37104004, 2023). "Our findings thus suggest that MALAT1 SNP rs3200401 is a potential indicator of obesity susceptibility and pathogenesis in children and adolescents." (PMID 37104004, 2023). "In conclusion, we found that the MALAT1 rs3200401 SNP is associated with the risk of obesity in Russian children and adolescents." (PMID 37104004, 2023). "The results showed that MALAT1 rs3200401 has a positive association with an individual’s susceptibility to obesity (p = 0.0009)." (PMID 37104004, 2023). "The data in the literature are diverse and controversial regarding the role of MALAT1 in obesity and related disorders." (PMID 38674413, 2024). "The wide range of MALAT1 functions makes it an interesting target in studies searching for drugs to prevent obesity development in humans." (PMID 38674413, 2024). "The literature on the role of MALAT1 in obesity and metabolic syndrome is limited and conflicting, but MALAT1 was recently found to be reduced in white adipose tissue from obese mice." (PMID 36653874, 2023). "This includes the widely studied MALAT1 and H19 lncRNAs, previously discovered in other contexts and more recently assigned to obesity-relevant roles." (PMID 37104004, 2023). "decreased the expression of long non-coding RNA MALAT1 and increased the expression of miR-320a, which are related to endothelial function, in children with obesity." (PMID 35813370, 2022). "The exact mechanisms linking TUG1 and MALAT1 to the pathogenesis of obesity cannot be ascertained according to the present study." (PMID 32368256, 2020). "Moreover, reduced MALAT1 expression in scWAT was also observed in genes (ob and db), as well as diet-induced obesity models." (PMID 38674413, 2024). "The role of MALAT1 was demonstrated in some metabolic disorders, like obesity and diabetes." (PMID 38424234, 2024). "There is limited and somewhat conflicting research on the role of MALAT1 in obesity." (PMID 38167433, 2024). "This study suggests that MALAT1 inhibition may have potential in the treatment of obesity and type 2 diabetes." (PMID 38674413, 2024). "Recently, many studies have suggested that lncRNAs, such as Metastasis Associated Lung Adenocarcinoma Transcript 1 (MALAT1) and Imprinted Maternally Expressed Transcript (H19), might participate in the pathogenesis of metabolic disorders such as obesity." (PMID 37104004, 2023). "In an attempt to understand the molecules involved in human obesity pathogenesis, we aimed to evaluate the expression of MALAT1 and TUG1 in visceral adipose tissues (VAT) and subcutaneous adipose tissues (SAT) of obese women, as compared to normal-weight women." (PMID 32368256, 2020). "The literature on the role of MALAT1 in obesity and related disorders is scarce and controversial." (PMID 32368256, 2020).